MIF (macrophage migration inhibitory factor)
Diseases named in the same sentence as MIF in open-access papers (continued):
Sharing a sentence is not in itself a finding about the gene and the disease.
cancer (continued). "Notably, we found an increased signaling of MIF-(CD74+CD44) in T-ICC between malignant cells and TAMs or T cells, which has been well documented to promote cancer progression." (PMID 35558087, 2022). "Another example is the potential of exosomal protein cargo, macrophage migration inhibitory factor (MIF), to reshape the phenotype of drug-sensitive cancer cells into temozolomide-resistant cells by positively modulating phosphoinositide 3-kinase (PI3K)/AKT signaling." (PMID 35055115, 2022). "MIF and MIF2 expression is dysregulated in cancers and neurodegenerative diseases." (PMID 34724273, 2022). "Regardless of tissue of origin and hormone responsiveness, the anti-proliferative activity of MIF in cancer cells has been found to be independent of nPRs." (PMID 36246881, 2022). "Collagens, MIF, MDK, APP, and laminin were detected as the most significant signaling, and the top ligand-receptor interactions THBS2/THBS3 (CAFs)—CD47 (cancer cells), MDK (CAFs)—NCL/SDC2/SDC4 (cancer cells) as potential therapeutic targets." (PMID 36352420, 2022). "AR, MIF, HSP90B1, and MAOA were expressed in more than 50% of cancer cells with high expression levels and may have potential therapeutic targets." (PMID 36452480, 2022). "In contrast to cancer, the different expression patterns of MIF and D-DT also support different roles of MIF and D-DT in noncancerous tissues." (PMID 35091838, 2022). "Also, the fluorogenic umbelliferone derivative exhibited high affinity to macrophage migration inhibitory factor (MIF) tautomerase, which was described as a regulator of the enzymatic activity, playing key roles in inflammation and cancer." (PMID 34946562, 2021). "Notably, EGFR and its receptors, including TGFB1, MIF, HBEGF, GRN, COPA, and AREG, were upregulated in cancer cells and fibroblasts." (PMID 34326696, 2021). "LE-KLK3 and LE-KLK4 both expressed macrophage inhibitory factor (MIF), a macrophage survival, activation and recruiting factor, with its receptor CD74 expressed by all prostate MNPs, and this interaction was attenuated in cancer samples." (PMID 34936871, 2021). "In addition, MIF has been identified as a HIF target gene in cells of the trachea, lungs, and in cancer cells." (PMID 32885302, 2020). "We and others have shown that MIF and DDT are involved in several diseases of different origins such as immunoinflammatory and autoimmune diseases, neurodegenerative and neuropsychiatric diseases, and cancer." (PMID 32155795, 2020). "MIF expression and secretion is elevated in most solid and hematogenous cancers and high MIF expression is a negative prognostic indicator in several cancer types." (PMID 33324425, 2020). "Circulating T-EVs from stage-I PDAC patients that later showed established liver metastasis had been improved by higher levels of MIF, as compared with patients whose cancer did not advance and healthy control cases." (PMID 33081785, 2020). "Growing evidence suggests a key role for MIF and DDT in the development of cancer." (PMID 31635049, 2019). "Though initially identified as a T cell-derived cytokine that inhibits macrophage migration, its pleiotropic effects on immune cells, cancer cells, as well as non-cancerous cells made MIF more enigmatic to the researchers." (PMID 31664114, 2019). "An anti-MIF mAb that has been studied in Phase II PoC in cancer patients as well as anti-CD74 mAb that is in clinical phase and would allow simultaneous blockade of MIF and DDT signaling are of even more relevant for more rapid application in the clinical setting." (PMID 31581595, 2019). "TRAIL treatment was also shown to enhance pro-inflammatory cytokine and chemokine production, including IL6, IL8, MCP1, CXCL1, and MIF, in various cancer cell types independent from TRAIL sensitivity although cytokines levels were higher in resistant cancer cells." (PMID 31333662, 2019). "H. pylori-positive cancer subgroup also showed significantly higher MIF level than H. pylori-negative control (P < 0.01)." (PMID 30742638, 2019).
cancer (continued). "The demonstrated evidence of the synergisms of MIF and DDT in the OS of NB study suggest that dual inhibitors of MIF and DDT could have even better therapeutic potential against NB and eventually other types of cancers than a single antagonist." (PMID 31635049, 2019). "As augmented levels of HSP90 and MIF are specifically upregulated in cancer cells, tailored inhibitors of HSP90 may represent alternative approaches for MIF inhibition in cancer." (PMID 29707160, 2018). "An M2 macrophage polarization was also compatible with the observed CD74 enriched expression pattern and the elevated levels of macrophage migration inhibitory factor (MIF) cytokine in the cancer specimens (data not shown)." (PMID 28216608, 2017). "Compared to adipose stem cell conditioned medium (ADSC-CM), hUCESC-CM contains low levels of factors involved in cancer progression, e.g., EGFR, FGF-4 and -9, intracellular adhesion molecule-3, IL6, IL6R, CCL7, macrophage migration inhibitory factor (MIF), soluble gp130 and VEGF-D." (PMID 28841158, 2017). "A pro-inflammatory environment also contributes to NKG2D down-regulation, as release of the pro-inflammatory macrophage migration inhibitory factor (MIF) after inflammatory stimuli, contributes to NKG2D down-regulation and impaired NK cell cytotoxicity in cancer patients." (PMID 28850071, 2017). "Given the compensation of eicosanoid production by COX-1 pathway, the possibility of utilizing nonspecific COX plus MIF inhibitors for cancer prevention and therapy cannot be ruled out." (PMID 29247872, 2017). "Inhibition of MIF expression (by anti-MIF or anti-CD74 antibodies or chemotherapy) or COX expression (by indomethacin) has shown encouraging results, which may hinge upon the type of cancer." (PMID 29247872, 2017). "MIF was shown to trigger cell proliferation by activation of the central kinases Akt and ERK, thereby promoting sustained activation and survival of immune cells and cancer cell proliferation." (PMID 27636991, 2016). "Our findings suggest that targeting MIF, via highly specific and stable compounds, such as ISO-66, may be effective for cancer treatment and stimulation of anticancer immune responses." (PMID 25050663, 2014). "Partly regulated by macrophage migration inhibitory factor (MIF), Th17 cells could produce higher levels of cytokines including TNF and IFN-γ, showing anti-cancer effect." (PMID 24386144, 2013). "Therefore, MIF and SCD1 inhibitors have high potential as drugs, because the safety of these inhibitors has been validated for various diseases other than cancer." (PMID 24167613, 2013). "MIF or SCD1 inhibitors have been used to restrict the growth or metastasis of many types of cancers, although not STS." (PMID 24167613, 2013). "This regulatory protein stabilization feature secures persistent MIF action in cancer cells independent of transcriptional and translational levels." (PMID 22973314, 2012). "At a threshold of 800 pg ml−1, MIF correctly detects 31 out of 51 cancers (61% sensitivity) and all non-cancers (100% specificity)." (PMID 19550422, 2009). "Seven up-regulated genes including CYC1, MIF, LAMB3, TUBB2, UBE2C and TRAP1 had been previously proposed as candidate common cancer biomarkers based on a previous extensive comparison among various cancers and normal tissues which did not, however, include NPC or NP." (PMID 18570662, 2008). "Both MIF and HIF-1 play critical roles in cancer and inflammation." (PMID 18493321, 2008). "This review synthesizes emerging evidence that CD74 functions as a “master regulator” of antigen presentation in cancer, integrating its canonical chaperone role with its noncanonical role in transcription regulation and in signaling via macrophage migration inhibitory factor." (PMID 41597203, 2026).
cancer (continued). "The downstream pathways activated by MIF include the mitogen‐activated protein kinase (MAPK), phosphoinositide 3‐kinase (PI3K), and nuclear factor kappa B (NF‐κB) pathways, which are frequently involved in cancer progression and are subject to epigenetic regulation." (PMID 38520216, 2024). "There is substantial evidence to support the pivotal roles of MIF and DDT in cancer progression and highlight their potential as promising and broadly applicable targets in oncology, arguing for the need for expanded research and clinical trials to establish their efficacy in cancer therapy." (PMID 38732068, 2024). "Based on the observations detailed above, we believe that is worth following up on the role of PARylation in the regulation of LCN2, MIF, and PAI-1 expression as it may contribute to the anticancer effect of PARylation of various different types of cancer with high abundance of infiltrating MΦs." (PMID 38612413, 2024). "Notably, we identified several key ligand-receptor pairs in TNChigh cancer cells and immune cells, including NECTIN2-TIGIT, MIF-(CD74+CD44), MDK-NCL, LAMB3-CD44, COL1A2-CD44, COL1A1-CD44, CD99-CD99, APP-CD74, and GZMB-PARD3 were identified in TNChigh cancer cells and immune cells." (PMID 38711034, 2024). "Additionally, a human-compatible DDT inhibitor as well as a dual MIF and DDT inhibitor have yet to be developed and studied in preclinical models to validate the hypothesis of targeting MIF and DDT as a synergistic therapeutic approach to cancer in patients." (PMID 38732068, 2024). "Similarly, LE-LE cancer cells could signal through adhesive ligand-receptor pairs LAMB3-ITGA6_ITGB4 and LAMB3-ITGA6_ITGB1, and inflammatory ligand-receptor pairs MIF-CD74_CD44." (PMID 37596273, 2023). "Accordingly, MIF not only signals through its cognate receptor CD74/invariant chain, but engages in high-affinity interactions with the CXC chemokine receptors CXCR2 and CXCR4 to promote atherogenic monocyte and T-/B-cell recruitment, cancer metastasis, and inflammation." (PMID 36094626, 2022). "To date, an immunotherapeutic vaccine targeting MIF for cancer treatment has not been introduced." (PMID 34389619, 2021). "Further, the selectivity differences seen between our covalently linked conformationally restricted versus non-linked versus hyper-restricted constructs may instruct for the design of dual-specificity inhibitors against both MIF and CXCL12, e.g. for future applications in cancer." (PMID 33239628, 2020). "However, in these approaches, the effect of MIF produced by normal cells on cancer cells (paracrine effects) is not being addressed." (PMID 31664114, 2019). "Indeed, MIF regulation has been studied in several virus-induced cancers, but it has never been examined in HPV-infected carcinomas." (PMID 30634708, 2019). "Moreover, we demonstrated MIF and COX-2 primary antibody-conjugated gold nanoparticles can be arranged on the surface of M2 macrophage as a fast alternative to analyze the immune profile of inflammation-induced cancer tissues by flow cytometry." (PMID 31102112, 2019). "However, these attempts do not address the contribution of MIF originating from stromal cells of cancer patients." (PMID 31664114, 2019). "Furthermore, cancer-related systemic inflammation promotes and maintains AF by inducing atrial structural remodeling, such as that in tumor necrosis factor (TNF)-α, nuclear factor (NF)-κB, and macrophage migration inhibitory factor (MIF)." (PMID 30386232, 2018).
cancer (continued). "It included a number of genes with obvious cancer relevance including CD44, catenin b1 (CTNNB1), vimentin (VIM), cathepsins B and S (CTSB, CTSS), MMP9, XIAP, JunD, numerous proto-oncogenes (REL, YES, SET, FGR, CRK), and HSP90AA1 (which is a chaperone which stabilizes MIF as a client)." (PMID 28957348, 2017). "Recently, a series of studies have enlightened that MIF governed angiogenesis, epithelial-mesenchymal transition (EMT), hypoxia and cell cycle in many kinds of human cancers including HNSCC, and indicated that MIF might be a potential driver and biomarker for HNSCC." (PMID 27788497, 2017). "In summary, the data reveal that MIF secretion in response to cancer therapy could have significant negative effects on patient outcome." (PMID 26741693, 2016). "On the basis of these results, we hypothesize that salivary MIF may not originate exclusively from OSCC cancer cells and, therefore, may not present a reliable marker for tumor diagnosis." (PMID 25289107, 2014). "However, the cancer cell growth assay is not the first report of the use of MIF or SCD1 inhibitors to retard cancer cell growth." (PMID 24167613, 2013). "As a proinflammatory cytokine, MIF counter-regulates the effects of glucocorticoids and stimulates the secretion of other cytokines such as tumor necrosis factor (TNF)-α and interleukin (IL)-1β, thus assuming a role in the pathogenesis of inflammatory, immune diseases and cancer." (PMID 16000172, 2005). "However, MIF loss does not obviously alter the growth of non-tumorigenic epithelial cells MCF-10A or mouse embryonic fibroblasts, and MIF knockout mice are normal without obvious defects, suggesting that the expression of MIF is more favorable for cancer cell growth rather than normal cells." (PMID 34012010, 2021). "Thus, the non-viral nanoparticles targeting primary macrophage MIF gene could lead to novel therapeutic strategy for cancers and inflammatory diseases." (PMID 25799489, 2015). "Moreover, although administered at low concentrations, they can still effectively and specifically target MIF irrespective of its origin, i.e., whether deriving from host and/or cancer cells." (PMID 25050663, 2014). "Since the same protein (MIF) was chosen for both normal vs. cancer and normal vs. benign lesions, it is likely that this protein plays a role in the inflammatory response to a lesion, whether benign or malignant, rather than in a role specific for cancer." (PMID 19476629, 2009). "Regarding the comparison of cancer grades and TNM stages in BC patients, there was no notable difference in serum MIF level that was observed." (PMID 38916819, 2024). "GAS, CXCL, complement, annexin, MIF, PROS and FGF signalling were relatively common interactions, although none was consistently significant across all cancers." (PMID 36772945, 2023). "Since MIF and DDT exert pleiotropic functions, it is not surprising that these cytokines have an intricate relationship with almost all the hallmarks of cancer." (PMID 36672343, 2023). "Fibrocytes secrete only IL23 and IFNγ, which were suppressed upon co-culture, whereas cancer cells or fibrocytes secrete CCL5, IL-1ra, CD54, CXCL10, MIF, CXCL1, IL-6, and IL-8, which was not affected by co-culture." (PMID 36241617, 2022). "Whereas the control tumors expressed HIF-1α in their cancer cell nuclei, 143B−/− masses were characterized by a complete absence of HIF-1α staining, in line with MIF downregulation." (PMID 31835761, 2019). "MIF has been shown to favor inflammatory responses and cancer-favoring mechanisms in previous experimental murine models of CRC, but none of these models was completely devoid of MIF." (PMID 31360118, 2019). "Among the 16 common cancer biomarkers identified as highly predictive by the previous study which did not include NPC samples, 6 genes (CYC1, MIF, LAMB3, TSTA3, TUBB2, and UBE2C) were found to be highly expressed in NPC by the study." (PMID 18570662, 2008).
cancer (continued). "However, currently no mechanistic studies are about how KSHV activates MIF signaling, especially which specific KSHV proteins or components are able to regulate MIF signaling in cancer cells." (PMID 41472252, 2025). "Many cancer-related soluble immunosuppressive molecules have negative effects on NK cell function, including TGF-β, IL-10, indoleamine 2,3-dioxygenase, prostaglandin E2 (PGE2) and macrophage migration inhibitory factor (MIF)." (PMID 36119047, 2022). "MIF inhibitors, particularly when acting on the MIF/CD74 axis, could be a very attractive strategy for cancer therapeutic intervention due to the nonphysiologic enzymatic activity of the cytokine that is evolutionary well-conserved." (PMID 28114961, 2017). "MIF and DDT are ubiquitous among immune and non-immune cell types, though their effects on stromal and myeloid-derived cells, such as macrophages, dendritic cells and early myeloid derived suppressor cells (MDSCs), have been largely characterized in cancer progression." (PMID 39028303, 2024).